ATP6V1A (ATPase H+ transporting V1 subunit A)
Description:
Catalytic subunit of the V1 complex of vacuolar(H+)-ATPase (V-ATPase), a multisubunit enzyme composed of a peripheral complex (V1) that hydrolyzes ATP and a membrane integral complex (V0) that translocates protons. V-ATPase is responsible for acidifying and maintaining the pH of intracellular compartments and in some cell types, is targeted to the plasma membrane, where it promotes acidification of the extracellular environment. The V-ATPase complex also acts as an activator for mTORC1 on lysosomal membrane by promoting the guanine nucleotide exchange factor (GEF) of the Ragulator complex, thereby enabling mTORC1 recruitment. In aerobic conditions, involved in intracellular iron homeostasis, thus triggering the activity of Fe(2+) prolyl hydroxylase (PHD) enzymes, and leading to HIF1A hydroxylation and subsequent proteasomal degradation. May play a role in neurite development and synaptic connectivity. (Microbial infection) Plays an important role in virion uncoating during Rabies virus replication after membrane fusion. Specifically, participates in the dissociation of incoming viral matrix M proteins uncoating through direct interaction.
Synonyms: ATP6A1; ATP6V1A1; VPP2; Vma1; VA68; ARCL2D; DEE93; HO68; IECEE3
Tractability: Small molecule: a structure with a bound ligand is known. Antibody: UniProt places it where antibodies can reach, with high confidence; its Gene Ontology location is reachable by antibodies, with high confidence. PROTAC: ubiquitination databases record sites on it; its protein half-life has been measured.
Target class: Enzyme; Hydrolase
Gene: Protein-coding gene on chromosome 3 (113,746,770 to 113,812,056, forward strand). Ensembl gene ENSG00000114573.
Subcellular location: Cytoplasm; Cytoplasm, cytosol; Cytoplasmic vesicle, secretory vesicle; Cytoplasmic vesicle, clathrin-coated vesicle membrane; Lysosome membrane
Subcellular location (Human Protein Atlas): Cytosol; Vesicles; Nucleoplasm
Pathways (Reactome):
Transport of small molecules: Ion channel transport; Transferrin endocytosis and recycling
Cellular responses to stimuli: Amino acids regulate mTORC1
Developmental Biology: Regulation of MITF-M-dependent genes involved in lysosome biogenesis and autophagy
Immune System: ROS and RNS production in phagocytes
Signal Transduction: Insulin receptor recycling
Gene Ontology:
Molecular function: guanyl nucleotide exchange factor activator activity; protein binding; proton-transporting ATPase activity, rotational mechanism; ATP binding; ATP hydrolysis activity; proton transmembrane transporter activity
Biological process: cellular response to amino acid stimulus; cellular response to increased oxygen levels; intracellular iron ion homeostasis; positive regulation of TORC1 signaling; endosomal lumen acidification; Golgi lumen acidification; intracellular pH reduction; lysosomal lumen acidification; proton transmembrane transport; regulation of macroautophagy; vacuolar acidification; ATP metabolic process; homeostatic process; synaptic vesicle lumen acidification
Cellular component: cytoplasm; cytosol; extracellular exosome; lysosomal membrane; lysosomal proton-transporting V-type ATPase complex; membrane; secretory granule; vacuolar proton-transporting V-type ATPase, V1 domain; endosome membrane; Golgi membrane; lysosome; plasma membrane; proton-transporting two-sector ATPase complex; proton-transporting V-type ATPase complex; vacuolar membrane; apical plasma membrane; clathrin-coated vesicle membrane; microvillus; presynapse; proton-transporting V-type ATPase, V1 domain; transport vesicle
Genetic constraint (gnomAD): Loss-of-function variants: 16 observed, 62.14 expected, observed/expected ratio (o/e) 0.26, 90% interval 0.17 to 0.39. The upper end of that interval is the gene's LOEUF score, 0.39, which puts it in group 1 of 6, group 1 being the genes least tolerant of losing a copy. Missense variants: 378 observed, 726.7 expected, observed/expected ratio (o/e) 0.52, 90% interval 0.48 to 0.57. Synonymous variants: 212 observed, 237.86 expected, observed/expected ratio (o/e) 0.89, 90% interval 0.8 to 1.
Gene-disease validity (ClinGen):
ClinGen rates the evidence that ATP6V1A causes each of these diseases.
autosomal recessive cutis laxa type 2D (autosomal recessive): Limited.
Homologues: Orthologues: chimpanzee ATP6V1A (100% identical), macaque ATP6V1A (99% identical), pig ATP6V1A (99% identical), guinea pig ATP6V1A (98% identical), mouse Atp6v1a (98% identical), rat Atp6v1a (98% identical), dog ATP6V1A (94% identical), rabbit ATP6V1A (94% identical), zebrafish atp6v1aa (93% identical), zebrafish atp6v1ab (93% identical), Drosophila melanogaster Vha68-2 (83% identical), Drosophila melanogaster Vha68-1 (83% identical), and 3 more. Paralogues in human: ATP6V1B2 (21% identical), ATP6V1B1 (21% identical), ATP5F1B (20% identical), ATP5F1A (16% identical).
Diseases named in the same sentence as ATP6V1A in open-access papers:
ATP6V1A is named in the same sentence as 82 diseases in open-access papers, as found by Europe PMC text mining. Sharing a sentence is not in itself a finding about the gene and the disease. The quoted sentences say what the papers report.
epilepsy (9 papers, 2020 to 2024). A brain disorder characterized by episodes of abnormally increased neuronal discharge resulting in transient episodes of sensory or motor neurological dysfunction, or psychic dysfunction. "NGS analysis of a multigene epilepsy panel detected a de novo heterozygous variant c.82G>A (p.Val28Met) in the ATP6V1A gene." (PMID 39336810, 2024). "Our review of reported patients with ATP6V1A dominant mutations shows that epilepsy is usually the first symptom." (PMID 40225911, 2024). "ATP6V1A variants, mainly clustering within the ATP synthase α/β family-nucleotide-binding domain, include early lethal encephalopathies and developmental encephalopathy in epilepsy." (PMID 36980356, 2023). "Moreover, ATP6V1A maturations were implicated in the onset of developmental encephalopathy with epilepsy, suggesting its role in regulating neuronal development." (PMID 34683848, 2021). "Mutation of the ATP6V1A gene causes encephalopathy with epilepsy." (PMID 32295833, 2020). "Many genes encoding subunits of V-ATPases, namely ATP6V0C, ATP6V1A, ATP6V0A1, and ATP6V1B2, have been associated with neurodevelopmental disorders and epilepsy." (PMID 37628590, 2023). "We strengthen the need to consider ATP6V1A-related diseases in the differential diagnosis of developmental delay without epilepsy (e.g., by including this gene in an NGS dedicated panel) when febrile seizures, acquired microcephaly, and/or enamel dysplasia are present." (PMID 39336810, 2024). "Although ATP6V1A mutations have traditionally been linked to severe neurodevelopmental disorders, often with early-onset epilepsy, they may exhibit milder, non-progressive phenotypes, challenging previous assumptions about the severity of ATP6V1A-related conditions." (PMID 39336810, 2024).
gastric cancer (5 papers, 2017 to 2022). A primary or metastatic malignant neoplasm involving the stomach. "Studies have reported overexpressed ATP6V1A in gastric tumor issues and its association with cancer prognosis, suggesting that ATP6V1A might be a target of gastric cancer treatment." (PMID 31024853, 2019). "The expression of ATP6V1A in gastric cancer tissue is significantly higher than that in normal tissue, and its expression is related to histological grade, lymph node metastasis, and vascular invasion." (PMID 33194650, 2020). "Knocking down the expression of ATP6V1A in vitro inhibits the proliferation and invasion ability of gastric cancer cells." (PMID 33194650, 2020). "ATP6V1A is known to drive proliferation and invasion in gastric cancer and ATP8A1 in non-small cell lung cancer." (PMID 31338326, 2019). "RNAi-mediated knockdown and over-expression of YY1 in HGC-27 and AGS gastric cancer cells in a reporter gene system led to corresponding changes in ATP6V1A mRNA and protein expression." (PMID 28592880, 2017). "Our results showed that, following the transfection of YY1 siRNA into the HGC-27 gastric cancer cells, ATP6V1A mRNA and protein levels were significantly decreased." (PMID 28592880, 2017). "Taken together, these results indicated that YY1 may play an important regulatory role in the transcription of ATP6V1A in gastric cancer cells." (PMID 28592880, 2017).
breast carcinoma (4 papers, 2020 to 2024). "Recently, an intriguing study reported that IGF2BP2 promoted the degradation of the RNA transcript encoding ATP6V1A, a catalytic subunit of the vacuolar ATPase, thus impairing lysosomal function and resulting in a unique secretome that greatly enhances breast cancer cell invasiveness." (PMID 38250159, 2024). "A recent study demonstrated that IGF2BP2 promoted the degradation of the RNA transcripts of the ATP6V1A gene, thereby impairing lysosomal function and resulting in a unique secretome that greatly enhances breast cancer cell invasiveness." (PMID 38250159, 2024).
cutis laxa (3 papers, 2020 to 2024). Cutis laxa (CL) is an inherited or acquired connective tissue disorder characterized by wrinkled, redundant and sagging inelastic skin associated with skeletal and developmental anomalies and, in some cases, with severe systemic involvement. "In the present study, we identified pathogenic variants in ATP6V1A as the cause of a severe cutis laxa phenotype in affected individuals from two unrelated families." (PMID 33320377, 2021). "In conclusion, we herein report on three additional affected individuals due to pathogenic variants in ATP6V1A as the cause for a severe cutis laxa phenotype." (PMID 33320377, 2021). "In addition, ATP6V1A recessive variants were shown to affect protein glycosylation in patients with cutis laxa." (PMID 40225911, 2024). "ATP6V1A variants were initially identified in three unrelated families with autosomal recessive cutis laxa type IID (ARCL2D; MIM:617403), which is a connective tissue disorder characterized by cutis laxa, facial dysmorphism, and hypotonia, as well as a history of neurological complications." (PMID 40225911, 2024).
Intellectual disability (3 papers, 2021 to 2024). "The gene–disease analysis further revealed that the ATP6V1A/BNIP3 and CAMK4/TIPRL/TOMM70 signatures were associated with several brain-related disorders, including developmental disabilities, schizophrenia, intellectual disabilities, abnormal cerebral white matter morphology, and mental retardation." (PMID 34683848, 2021).
viral infection (3 papers, 2021 to 2025). "We focused on the catalytic subunit of V-ATPase-ATP6V1A for further study based on previous findings that ATP6V1A influences the pH of endosomes and that the acidic endosomal environment is vital for the early stage of viral infection." (PMID 33208464, 2021). "However, the detailed molecular basis for how ATP6V1A affects viral infection remains unclear." (PMID 33208464, 2021). "In addition, they report the interaction of two subunits, ATP6AP1 and ATP6V1A, with SARS-CoV-2 non-structural protein 6 and membrane protein, suggesting a direct involvement of V-ATPase members in viral infection." (PMID 38674105, 2024).
Alzheimer disease (2 papers, 2021 to 2024). A progressive, neurodegenerative disease characterized by loss of function and death of nerve cells in several areas of the brain leading to loss of cognitive function such as memory and language. "The objective of this study was to investigate the potential molecular mechanisms of ATPase H+ transporting V1 subunit A (ATP6V1A) underlying Alzheimer's disease (AD)." (PMID 33981384, 2021). "The ATP6V1A gene was also identified as a disease driver in a parallel study characterizing the molecular heterogeneity of Alzheimer disease (AD), by using an integrative network approach on 1543 transcriptomes across five brain regions in two AD cohorts." (PMID 39273013, 2024). "A multi-omic molecular analysis of late-onset Alzheimer disease (LOAD) across four brain regions in 364 donors with varying cognitive and neuropathological phenotypes identified ATP6V1A as a top key regulator of the most dysregulated neuronal subnetwork in LOAD." (PMID 39273013, 2024).
developmental and epileptic encephalopathy 93 (2 papers, 2022 to 2024). "The ATPase H+ transporting V1 subunit A (ATP6V1A) gene that encodes V-ATPase subunit A, have been reported to be associated with developmental and epileptic encephalopathy 93 (DEE-93, MIM: 618012)." (PMID 35600075, 2022). "Developmental and epileptic encephalopathy 93 (DEE93) is a new defined autosomal dominant neurologic disorder caused by heterozygous mutations in the ATP6V1A gene on chromosome 3q13." (PMID 40225911, 2024).
endometrial cancer (2 papers, 2019 to 2021). Primary or metastatic malignant neoplasm involving the endometrium (mucous membrane that lines the endometrial cavity). "Other candidate genes found to be associated with endometrial cancer, ATP6V1A and ATP8A1 act as oncogenes." (PMID 31338326, 2019). "For example, ATP6V1A (one of the 12 most important genes identified in our study) has been associated with endometriosis severity and endometrial receptivity, and is known to be an oncogene in endometrial cancer." (PMID 33901012, 2021). "Seven genes, including RBM12, NDUFB6, ATP6V1A, RECK, SLC35E1, RFX3 (Bonferroni-corrected P < 0.05) and ATP8A1 (suggestive P < 10−5), and one long non-coding RNA, DLGAP4-AS1 (Bonferroni-corrected P < 0.05), were associated with endometrial cancer." (PMID 31338326, 2019).
Epileptic encephalopathy (2 papers, 2023 to 2024). A condition in which epileptiform abnormalities are believed to contribute to the progressive disturbance in cerebral function. "Up to now, 31 patients with ATP6V1A mutations presenting epileptic encephalopathy have been reported." (PMID 40225911, 2024).
lung carcinoma (2 papers, 2024). "In contrast, depletion of FBXO9 reduced ATP6V1A ubiquitination, resulting in increased V-ATPase assembly and vesicular acidification, thus promoting pro-metastatic Wnt signaling and metastasis of lung cancer cells." (PMID 38486234, 2024). "We initially reduced FBXO9 expression in A549 lung cancer cells by siRNA transfection to investigate the effect of ATP6V1A ubiquitination on V-ATPase." (PMID 38486234, 2024). "Hence, these in vivo results confirm the potential role of FBXO9 as an inhibitory protein against the migration, tumor sphere growth, and metastasis of lung cancer cells by promoting ATP6V1A ubiquitination." (PMID 38486234, 2024). "Collectively, these findings provide substantial evidence supporting the significant role of FBXO9-mediated ATP6V1A ubiquitination (which hinders V-ATPase assembly) in suppressing Wnt/β-catenin signaling and EMT in lung cancer cells." (PMID 38486234, 2024). "As previous experiments showed that FBXO9 suppresses V-ATPase through ATP6V1A ubiquitination, we sought to explore the relationship between FBXO9 and V-ATPase in the regulation of Wnt/β-catenin signaling in lung cancer cells." (PMID 38486234, 2024). "Importantly, the direct inhibition of FBXO9-mediated ATP6V1A ubiquitination by an interaction inhibitory peptide not only prevents cancer cell migration and sphere formation but also hinders the metastasis of lung cancer cells in a mouse model." (PMID 38486234, 2024).
microcephaly (2 papers, 2021 to 2024). A congenital or acquired developmental disorder in which the circumference of the head is smaller than normal for the person's age and sex. "Moreover, acquired microcephaly and enamel dysplasia are frequently reported in ATP6V1A-related disorders (35% and 38%, respectively)." (PMID 39336810, 2024).
Salmonella Infections (2 papers, 2021 to 2022). Infections with bacteria of the genus SALMONELLA. "A member of V-ATPase, ATP6V1A, was reported to participate in the defense against salmonella infection of pigs and human autophagy." (PMID 36077519, 2022). "ATP6V1A targeted by miR-143 inhibits intracellular salmonella growth in macrophages in pig, demonstrating that ATP6V1A plays important roles in the development of salmonella infection." (PMID 33208464, 2021).
schizophrenia (2 papers, 2016 to 2021). A major psychotic disorder characterized by abnormalities in the perception or expression of reality. "From the proteins involved in other energy pathways, vacuolar ATP synthases (ATP6V1A, ATP6V1B2, ATP6V0A1) and creatine kinase (CKB) were consistently found with differential abundance in all of the investigated brain regions of schizophrenia patients." (PMID 26909022, 2016).
autosomal recessive cutis laxa type 2D (1 paper, 2021). "Pathogenic variants affecting ATP6V1A, encoding the A subunit of the V1 sector have been shown as the cause of autosomal recessive cutis laxa type 2D (ARCL2D; OMIM: 617403)." (PMID 33320377, 2021). "Besides cutis laxa, muscular hypotonia and cardiac abnormalities are hallmarks of autosomal recessive cutis laxa type 2D (ARCL2D) due to pathogenic variants in ATP6V1A encoding subunit A of the v‐ATPase." (PMID 33320377, 2021).
Cerebral visual impairment (1 paper, 2025). A form of loss of vision caused by damage to the visual cortex rather than a defect in the eye. "Lastly, ATP6V1A has been identified as a candidate gene associated with cerebral visual impairment (CVI)." (PMID 40282202, 2025).
cognitive decline (1 paper, 2024). "Phosphorylation levels in these networks were inversely related to learning and linked to synaptic dysfunction, cognitive decline, and dementia including Atp6v1a and Itsn1." (PMID 38542311, 2024).
Cognitive impairment (1 paper, 2021). Abnormal cognition is characterized by deficits in thinking, reasoning, or remembering. "These were important processes of V-ATPase deficiency contributing to cognitive impairment and neuronal degeneration, consistent with our findings of the participation of low ATP6V1A-mediated synaptic vesicle cycle in AD pathogenesis." (PMID 33981384, 2021).
dysautonomia (1 paper, 2023). An acute or chronic disorder, affecting the sympathetic or parasympathetic nervous system. "Its associated disease (M191900) has joint pain, muscle aches, and symptoms of mast cell activation (M191900), as well as a tissue laxity–dysautonomia theme echoed by the ATP6V1A gene-associated lax skin disease (M617403) that has tall stature, aortic dilation, and joint contractures." (PMID 37504295, 2023).
E. coli infection (1 paper, 2023). "Further qRT-PCR assays showed that representative genes of phagosome maturation were significantly upregulated in response to E. coli infection including ATP6V1A, ATP6V1B2, BF2, CTSS, and TFRC, while COLEC12 was downregulated at 72 h." (PMID 36411420, 2023).
endometriosis (1 paper, 2021). The growth of functional endometrial tissue in anatomic sites outside the uterine body. "MiRNA-15a-5p and ATPase H+ transporting V1 subunit A (ATP6V1A) have previously been associated with endometriosis, and exhibited high topological significance in our analysis." (PMID 33901012, 2021). "Circ_0026129, miRNA-15a-5p and ATP6V1A were at the center of the network and were differentially expressed between exosomes from endometriosis patients and controls, confirming the reliability of our RNA sequencing results." (PMID 33901012, 2021). "We identified 12 endometriosis-associated exosomal RNA biomarkers, and found that circ_0026129, miRNA-15a-5p and ATP6V1A were at the center of the endometriosis-related exosomal ceRNA network." (PMID 33901012, 2021). "This de-repression may enhance the release of ATP6V1A from endometrial stromal cells to recipient cells in the uterine or abdominal cavity, thus contributing to the pathogenesis of endometriosis." (PMID 33901012, 2021). "Our functional annotation suggested that the identified hub genes were strongly associated with endometriosis, and that the circ_0026129/miRNA-15a-5p/ATP6V1A ceRNA network may be important for the development of endometriosis." (PMID 33901012, 2021). "The upregulated gene ATP6V1A was involved in ‘mTOR signaling’, an enriched KEGG pathway known to contribute to the development of endometriosis." (PMID 33901012, 2021).